WTIP (WT1 interacting protein)
Description:
Adapter or scaffold protein which participates in the assembly of numerous protein complexes and is involved in several cellular processes such as cell fate determination, cytoskeletal organization, repression of gene transcription, cell-cell adhesion, cell differentiation, proliferation and migration. Positively regulates microRNA (miRNA)-mediated gene silencing. Negatively regulates Hippo signaling pathway and antagonizes phosphorylation of YAP1. Acts as a transcriptional corepressor for SNAI1 and SNAI2/SLUG-dependent repression of E-cadherin transcription. Acts as a hypoxic regulator by bridging an association between the prolyl hydroxylases and VHL enabling efficient degradation of HIF1A. In podocytes, may play a role in the regulation of actin dynamics and/or foot process cytoarchitecture (By similarity). In the course of podocyte injury, shuttles into the nucleus and acts as a transcription regulator that represses WT1-dependent transcription regulation, thereby translating changes in slit diaphragm structure into altered gene expression and a less differentiated phenotype. Involved in the organization of the basal body (By similarity). Involved in cilia growth and positioning (By similarity).
Tractability: No criterion of Open Targets' tractability assessment is met for any kind of drug.
Gene: Protein-coding gene on chromosome 19 (34,481,682 to 34,512,304, forward strand). Ensembl gene ENSG00000142279.
Subcellular location: Cell junction, adherens junction; Nucleus; Cytoplasm, P-body
Pathways (Reactome):
Cellular responses to stimuli: Oxygen-dependent proline hydroxylation of Hypoxia-inducible Factor Alpha
Gene Ontology:
Molecular function: protein binding; transcription corepressor activity
Biological process: miRNA-mediated gene silencing by inhibition of translation; miRNA-mediated post-transcriptional gene silencing; negative regulation of hippo signaling; response to hypoxia; cytoskeleton organization; regulation of DNA-templated transcription; negative regulation of DNA-templated transcription
Cellular component: P-body; adherens junction; nucleus; transcription regulator complex
Genetic constraint (gnomAD): Loss-of-function variants: 23 observed, 34.42 expected, observed/expected ratio (o/e) 0.67, 90% interval 0.48 to 0.95. The synonymous counts are far from expectation, so gnomAD's model fits this gene poorly and the ratio says little. Missense variants: 615 observed, 488.54 expected, observed/expected ratio (o/e) 1.26, 90% interval 1.18 to 1.35. Synonymous variants: 311 observed, 210.63 expected, observed/expected ratio (o/e) 1.48, 90% interval 1.35 to 1.62.
Homologues: Orthologues: chimpanzee WTIP (99% identical), pig WTIP (95% identical), macaque WTIP (91% identical), dog WTIP (88% identical), mouse Wtip (85% identical), rat Wtip (84% identical), tropical clawed frog wtip (62% identical), zebrafish wtip (60% identical), guinea pig WTIP (57% identical). Paralogues in human: LIMD1 (45% identical), AJUBA (42% identical).
Diseases named in the same sentence as WTIP in open-access papers:
WTIP is named in the same sentence as 17 diseases in open-access papers, as found by Europe PMC text mining. Sharing a sentence is not in itself a finding about the gene and the disease. The quoted sentences say what the papers report.
colon cancer (3 papers, 2020 to 2022). "SUNO1 affects DDX5 to regulate the recruitment of RNA polymerase II to a the WTIP cis promoter, enhancing the transcription of WTIP, and promoting the development of colon cancer." (PMID 35992805, 2022). "Interestingly, a major fraction of these genes (71%), including WTIP, showed positive correlation in expression with SUNO1 across colon cancer patients, implying that SUNO1 potentially regulates the expression of these genes even in cancer tissue samples." (PMID 33108271, 2020). "We can state that only Ajuba and not its closely related LIM domain family members WTIP and LIMD1 are significantly increased in colon cancer compared to adjacent non-tumor tissues." (PMID 32679899, 2020).
hypospadias (2 papers, 2015 to 2025). Hypospadias is the displacement of the urethral meatus on the ventrum of the penis. "19q13.11 deletions and the Wilms tumor interacting protein (WTIP) gene result in hypospadias, making it a possible reason for this genital abnormality due to its well-known interaction with WT1." (PMID 40290553, 2025). "This hypothesis can be ruled out for SCGB2B2 since this gene is not expressed in skin cells and is not likely for WTIP gene because its haploinsuffiency has been pointed as a cause for hypospadias." (PMID 25883683, 2015).
breast carcinoma (1 paper, 2024). "Next, we confirmed the significantly downregulated mRNA expression of AJUBA, WTIP, SAMD4A, and NOCT and moderately increased expression of PNRC1 in YAP/TAZ knockdown HCT116 cells by qPCR analysis; this pattern was also observed in A549 lung cancer cells and MDA-MB-231 breast cancer cells." (PMID 39046443, 2024).
cervical cancer (1 paper, 2021). A primary or metastatic malignant neoplasm involving the cervix. "In cervical cancer cells, downregulation of WTIP abolished BRCA2-mediated centrosome localization and resulted in abnormal cell division, suggesting that WTIP might be involved in the development of cervical cancer." (PMID 34930905, 2021).
colorectal cancer (1 paper, 2024). A primary or metastatic malignant neoplasm that affects the colon or rectum. "Mechanistically, both transcriptional activation of the P-body-related genes SAMD4A, AJUBA, and WTIP and transcriptional suppression of the tumor suppressor gene PNRC1 are involved in enhancing the effects of YAP/TAZ on P-body formation in colorectal cancer (CRC) cells." (PMID 39046443, 2024).
focal segmental glomerulosclerosis (1 paper, 2019). A renal disorder characterized by sclerotic lesions in the glomeruli. "Modulation of WTIP can lead to the kidney-cell scarring (e.g., focal segmental glomerulosclerosis) that is characteristic in diabetes mellitus." (PMID 31092860, 2019).
head/neck cancers (1 paper, 2021). "For bladder, kidney and head/neck cancers, proteins TRIP6, WTIP, and Ajuba, respectively, showed the highest mutational frequency." (PMID 33808029, 2021).
non-small cell lung carcinoma (1 paper, 2021). A group of at least three distinct histological types of lung cancer, including non-small cell squamous cell carcinoma, adenocarcinoma, and large cell carcinoma. "For example, WTIP has a crucial role in cell proliferation and downregulation of WTIP is associated with poor prognosis and survival of non-small-cell lung cancer patients." (PMID 33808029, 2021).
tumor (8 papers, 2016 to 2025). "Our results combined with previous results suggest that loss of WTIP tumor-suppressive functions due to genetic defects may represent a common feature of tumorigenesis in various cancers." (PMID 34930905, 2021). "Collectively, our results suggest that WTIP is a tumor suppressor and a potential target for therapeutic intervention in AML." (PMID 34930905, 2021). "Other example of the last advances in this field is the detection of the scaffold WT1-interacting protein (WTIP) as a novel tumor suppressor down-modulated in NSCLC." (PMID 31744117, 2019). "Data from The Cancer Genome Atlas (TCGA) database also showed that WTIP expression is significantly downregulated in tumor tissues compared to matched normal tissue from patients with LUAD or LUSC." (PMID 30690883, 2019). "Together, these results suggest that WTIP inhibits tumor growth and induces apoptosis in vivo." (PMID 34930905, 2021). "Emerging evidence suggests that WTIP is a candidate tumor suppressor." (PMID 34930905, 2021). "Previous studies suggested that WTIP is a candidate tumor suppressor." (PMID 34930905, 2021). "Our results suggest that WTIP is a tumor suppressor and may be a potential target for NSCLC treatment." (PMID 30690883, 2019). "Thus, we speculated that WTIP functions as a tumor suppressor and inhibits cell proliferation in NSCLC." (PMID 30690883, 2019). "Mechanistic studies reveal that the apoptotic function of WTIP is mediated by upregulation and nuclear translocation of FOXO3a, a member of Forkhead box O (FOXO) transcription factors involved in tumor suppression." (PMID 34930905, 2021). "In ESCC tissue, amplification of genes such as WTIP and MCL1 (chromosome 19) may enhance tumor invasiveness and anti-apoptotic capacities, potentially influencing tumor progression and therapeutic response." (PMID 40963872, 2025). "Interestingly, studies in other cancers had already identified WTIP, NAP1L3, and CCDC91, as relevant genes for tumor progression." (PMID 37772256, 2023). "Comparative analysis showed that the mRNA and protein levels of WTIP were also differentially repressed in almost all NSCLC tumor tissues compared with those in matched adjacent nontumor tissues." (PMID 30690883, 2019). "Furthermore, the BSP assay results showed that the analyzed CpG islands were hypermethylated and that the levels of hypermethylation were inversely correlated with the level of WTIP in NSCLC cell lines and tumor specimens from NSCLC patients." (PMID 30690883, 2019). "Here, we analyzed the mRNA levels of AJUBA and two other AJUBA family members, WTIP and LIMD1, in ESCC tumor tissues and in their matched adjacent non-tumor tissues." (PMID 27172796, 2016). "However, the mRNA levels of WTIP and LIMD1 were not dysregulated in tumor tissues." (PMID 27172796, 2016).
cancer (5 papers, 2019 to 2024). A tumor composed of atypical neoplastic, often pleomorphic cells that invade other tissues. "Increasing evidence has shown that WT1‐interacting protein (WTIP) plays important roles both physiologically and pathologically in humans; however, the role of WTIP in cancer is unknown." (PMID 30690883, 2019). "However, there are little data regarding whether WTIP has an important role in cancer development and progression, which needs to be elucidated." (PMID 30690883, 2019). "To date, the expression of WTIP in cancers has never been investigated." (PMID 30690883, 2019).
WTIP also shares sentences with these, for which no sentence is quoted: acute myeloid leukemia (1 paper); Hurler syndrome (1); leukemia (1); lung adenocarcinoma (1); lung carcinoma (1); lung squamous cell carcinoma (1); Obesity (1).